SNORD116-2 (small nucleolar RNA, C/D box 116-2)
Synonyms: HBII-85-2
Gene: Small nucleolar RNA gene on chromosome 15 (25,054,210 to 25,054,304, forward strand). Ensembl gene ENSG00000207001.
Gene Ontology:
Biological process: RNA processing
Cellular component: nucleolus
Homologues: Orthologues: chimpanzee SNORD116 (97% identical), macaque SNORD116 (95% identical), rabbit SNORD116 (88% identical), rabbit SNORD116 (87% identical), rabbit SNORD116 (86% identical), rabbit SNORD116 (85% identical), rabbit SNORD116 (84% identical), rabbit SNORD116 (82% identical), rabbit SNORD116 (81% identical), rabbit SNORD116 (79% identical), rabbit SNORD116 (77% identical). Paralogues in human: SNORD116-6 (99% identical), SNORD116-4 (97% identical), SNORD116-1 (96% identical), SNORD116-3 (96% identical), SNORD116-8 (96% identical), SNORD116-9 (96% identical), SNORD116-5 (95% identical), SNORD116-7 (95% identical), SNORD116-14 (87% identical), SNORD116-17 (86% identical), SNORD116-19 (86% identical), SNORD116-21 (86% identical), and 20 more.